Y_RNA (Y RNA )
Gene: Miscellaneous RNA gene on chromosome 2 (233,379,843 to 233,379,955, reverse strand). Ensembl gene ENSG00000201013.
Homologues: Orthologues: chimpanzee Y_RNA (98% identical), macaque Y_RNA (90% identical), mouse Gm55481 (64% identical). Paralogues in human: Y_RNA (81% identical), RNY1 (81% identical), Y_RNA (80% identical), Y_RNA (79% identical), RNY1P11 (78% identical), Y_RNA (78% identical), RNY1P12 (77% identical), Y_RNA (77% identical), RNY1P10 (76% identical), Y_RNA (76% identical), RNY1P15 (75% identical), RNY1P8 (75% identical), and 92 more.